CD8A (CD8 subunit alpha)
Description:
Integral membrane glycoprotein that plays an essential role in the immune response and serves multiple functions in responses against both external and internal offenses. In T-cells, functions primarily as a coreceptor for MHC class I molecule:peptide complex. The antigens presented by class I peptides are derived from cytosolic proteins while class II derived from extracellular proteins. Interacts simultaneously with the T-cell receptor (TCR) and the MHC class I proteins presented by antigen presenting cells (APCs). In turn, recruits the Src kinase LCK to the vicinity of the TCR-CD3 complex. LCK then initiates different intracellular signaling pathways by phosphorylating various substrates ultimately leading to lymphokine production, motility, adhesion and activation of cytotoxic T-lymphocytes (CTLs). This mechanism enables CTLs to recognize and eliminate infected cells and tumor cells. In NK-cells, the presence of CD8A homodimers at the cell surface provides a survival mechanism allowing conjugation and lysis of multiple target cells. CD8A homodimer molecules also promote the survival and differentiation of activated lymphocytes into memory CD8 T-cells.
Synonyms: p32; CD8alpha; CD8; IMD116; Leu2
Tractability: Small molecule: a structure with a bound ligand is known. Antibody: UniProt places it where antibodies can reach, with high confidence; its Gene Ontology location is reachable by antibodies, with high confidence; UniProt predicts a signal peptide or a membrane-spanning region; the Human Protein Atlas places it where antibodies can reach. PROTAC: its protein half-life has been measured.
Gene: Protein-coding gene on chromosome 2 (86,784,610 to 86,808,396, reverse strand). Ensembl gene ENSG00000153563.
Subcellular location: Cell membrane (Isoform 1); Secreted (Isoform 2)
Subcellular location (Human Protein Atlas): Plasma membrane
Pathways (Reactome):
Immune System: Immunoregulatory interactions between a Lymphoid and a non-Lymphoid cell
Gene Ontology:
Molecular function: MHC class I protein complex binding; protein binding; coreceptor activity; MHC class I protein binding
Biological process: T cell activation; T cell receptor signaling pathway; adaptive immune response; antigen processing and presentation; cell surface receptor protein tyrosine kinase signaling pathway; cytotoxic T cell differentiation; immune response; T cell mediated immunity; cell surface receptor signaling pathway
Cellular component: external side of plasma membrane; extracellular region; plasma membrane; plasma membrane raft; receptor complex; T cell receptor complex
Genetic constraint (gnomAD): Loss-of-function variants: 24 observed, 22.55 expected, observed/expected ratio (o/e) 1.06, 90% interval 0.77 to 1.5. The upper end of that interval is the gene's LOEUF score, 1.5, which puts it in group 6 of 6, group 1 being the genes least tolerant of losing a copy. Missense variants: 349 observed, 290.03 expected, observed/expected ratio (o/e) 1.2, 90% interval 1.1 to 1.32. Synonymous variants: 164 observed, 134.5 expected, observed/expected ratio (o/e) 1.22, 90% interval 1.07 to 1.39.
Homologues: Orthologues: chimpanzee CD8A (99% identical), macaque CD8A (88% identical), dog CD8A (62% identical), pig CD8A (60% identical), guinea pig CD8A (56% identical), rat Cd8a (51% identical), mouse Cd8a (50% identical), tropical clawed frog CD8A (28% identical), zebrafish cd8a (16% identical).
Diseases named in the same sentence as CD8A in open-access papers:
CD8A is named in the same sentence as 1,684 diseases in open-access papers, as found by Europe PMC text mining. Sharing a sentence is not in itself a finding about the gene and the disease. The quoted sentences say what the papers report.
melanoma (3,763 papers, 2002 to 2026). A malignant, usually aggressive tumor composed of atypical, neoplastic melanocytes. "Similar to patients with melanoma, those with lung squamous cell carcinoma have a trend toward improved survival in association with high CD8a expression." (PMID 40553564, 2025). "In the immune compartments of melanoma tissues, proteins implicated in immune response were enriched in the responders after treatment, including CD8A, CD19/CD20, and CD45RO." (PMID 34188042, 2021). "The clinical relevance of the GEF-H1 immune pathway is supported by our TCGA analysis, which shows a significant association of CD8A to the GEF-H1 immune gene signature in patients with melanoma, head and neck cancer, and uterine cancer." (PMID 31553907, 2019). "Our findings indicate a positive correlation between tumor‐intrinsic IL4I1 expression and the expression of HLA‐A/‐B/‐C, B2M, and genes associated with CTL activation (GZMB, GZMA, CD8A, IFNG) in melanoma patients." (PMID 40583248, 2025). "To observe CD8+ cell interactions with melanoma in vivo, we created a transgenic (Tg) zebrafish line that labels cells expressing cd8a." (PMID 41109214, 2025). "We found that CD8α+ cells preferentially localized to mitfa− areas that form pockets lined by melanoma cells —here termed “CRATERs”—in all melanoma tumors imaged during this study (>100 fish)." (PMID 41109214, 2025). "This approach produces low-pigmented tumors in lower frequency but enabled melanoma generation in endothelial reporting or Tg(cd8a:EGFP;lck:mCherry) zebrafish." (PMID 41109214, 2025). "Using a reverse translational approach, we initially assessed the prognostication power of TIMP1 in comparison with CD8A in the GDC-TCGA-SKCM melanoma dataset, a cornerstone model for ICT research." (PMID 38777826, 2024). "We observed positive correlations between three types of NLS and T-cell receptor-associated gene expression signatures, such as CD8A, CD3G, CCL5, TIGT, LCK and IKZF3 in lung cancers and primary melanomas after adjusting clinical factors." (PMID 37100920, 2023). "Melanoma cells and CTLs were identified by Sox10 (a nuclear marker of melanocytic lineage, orange) and CD8 (a CTL marker, purple) expression respectively and cell lysosomal content was identified by CD107a staining (black)." (PMID 37932311, 2023). "The expression level of ACSL4 in bladder cancer and melanoma patients was positively correlated with their survival, which was also parallel to the expression levels of CD8A and IFN-γ and the T-cell signature." (PMID 35847022, 2022). "IL-12 inhibits melanoma progression via increasing the infiltration of NK cells and CD8α+ T cells, and a decreased presence of CD4+Foxp3+ regulatory T cells." (PMID 36428682, 2022). "Here, we demonstrate that CD8α ALN-1 drives antitumor CD8+ T cell responses in subcutaneous (s.c.)melanoma (B16) and Lewis lung carcinoma (LLC) models." (PMID 34772757, 2021). "The expresson level of CD8+ T cells markers including CD8A, GZMB, NKG7, etc., was all shown to be higher in low risk melanoma patients." (PMID 34040608, 2021). "Heightened dual expression of the ligands for CCR5 and CXCR3 (CCL5 and CXCL9, respectively) positively correlates with the amount of tumor CD8a transcripts and patient survival in cancers of the ovary, breast, lung, colon, as well as melanoma." (PMID 34354714, 2021). "For example, imiquimod, a TLR7 agonist, triggers CCL2 secretion from B16-F10-resident mast cells to mobilize anti-tumor CD8α+ plasmacytoid DCs to clear B16-F10-melanomas in a IFNAR1-dependent manner." (PMID 33922465, 2021). "In absolute count, CD8α− γδ T cells are less frequent in melanoma-bearing pigs compared to healthy pigs." (PMID 32180771, 2020).
melanoma (continued). "Nevertheless, in melanoma-bearing animals, we found a higher proportion and an equal absolute count of CD8α+ γδ T cells, which seems to stain more mature cells." (PMID 32180771, 2020). "In line with our findings, the inoculation of melanoma cells in mice was reported to decrease B and CD8α + T lymphocytes, increase CD4+ T lymphocytes and NK cells percentages and activate markers of NK in blood." (PMID 32180771, 2020). "The high expression of IRF1, JAK2, CD8A, STAT5B, and SELL was connected with a low risk of death and was a protective factor of melanoma." (PMID 32316408, 2020). "Individual immunotherapy panel markers CD274, PDCD1LG2, CD8A, IRF1 and a combined L1/L2 mRNA levels show promising associations with melanoma immunotherapy outcome." (PMID 31533832, 2019). "Tumors expressing β-catenin showed lack of recruitment of the Batf3-lineage DCs expressing the surface markers CD103 or CD8α as a result of insufficient production of the critical chemokine CCL4 by the melanoma cells." (PMID 30477280, 2018). "In melanomas, tumor-specific Th17 cells led to the recruitment on CD8α+ DCs and activation of tumor-specific CD8+ T-cells, which were crucial for the prevention of tumor development." (PMID 29048384, 2017). "IL-17−/− mice bearing B16 melanoma also exhibit increased lung metastases associated with reduced numbers of CD4+, CD8+ T cells, granulocytes, and CD11c+CD11b+ and CD11c+CD8a+ DCs at the tumor sites." (PMID 24454480, 2013). "Moreover, CD8A and PRF1 expression inversely correlate with LDH‐A, thereby corroborating that a lactate‐rich environment negatively impacts on the CD8‐mediated antitumour immunity in melanoma." (PMID 39888245, 2025). "Furthermore, in a longitudinal cytotoxicity assay, coexpression of CD8α/β improved the control of A375, a melanoma cell line that endogenously expresses NY-ESO-1." (PMID 39910194, 2025). "Additionally, type I IFNs are important for innate immune recognition of growing melanomas and promote the intra-tumoral accumulation of CD8α+ dendritic cells (DCs) in vivo." (PMID 40647561, 2025). "In addition, genetic depletion of mPGES-1 significantly slowed the growth of BrafV600E murine melanoma tumors via the increased infiltration of CD8a+ T cells and CD8a+ DCs and thus improved anti-PD-1 efficacy in a syngeneic mouse model." (PMID 37529399, 2023). "Moreover, we analyzed the expression level of gene CD3E, CD4, CD8A, GZMB, NKG7, TCF7 and TRBC2, the well-known markers for CD8+ T cells, and they were all shown to have significantly higher expression level in melanoma patients with low risk." (PMID 34040608, 2021). "As expected, initial analysis of zebrafish tumors indicated significantly reduced expression of the pan–T cell marker lck as well as cd8α and cd4-1, implying an overall reduction of T cells during the progression from radial growth phase melanoma to nodular tumors." (PMID 27694495, 2016). "Within the DC compartment, CD8α+ DCs were required to respond to type I IFN and to prime anti-tumor T cell responses in a pre-clinical melanoma model, as Batf3−/− mice, in which CD8α+ DCs fail to develop, generate very poor spontaneous anti-tumor T cell responses." (PMID 25914882, 2015). "Purified CD4+ T cells were stimulated with beads coated with anti-CD3 and anti-CD28 antibodies and co-transduced with a lentivirus expressing codon-optimized CD8α and individual CD8β isoforms and a second lentivirus expressing TCRαβ from a CD8 dependent TCR recognizing the melanoma antigen NY-ESO-1." (PMID 23533620, 2013). "Importantly, targeting CLEC9A on CD8α+ DCs efficiently induced CD8+ T cell responses and when combined with an adjuvant could both prevent the development as well as mediate the eradication of B16 melanoma lesions." (PMID 28536413, 2015). "Using the TCGA melanoma (SKCM) RNA-seq dataset, we correlated MBNL expression with CD8A gene expression as a proxy for tumor T-cell infiltration." (PMID 40305509, 2025).
melanoma (continued). "Our data revealed heightened expression of CD8+ T cell markers (CD8a and CD8b) and NK cell markers (NCR1 and NCR3) in melanoma patients with elevated levels of cGAS/CCL5/CXCL10." (PMID 38506049, 2024). "The heatmap displayed that melanomas with high IRE1α activity have increased expressions of TIL signature molecules like IFNG, GZMB, CD8A and CXCL10." (PMID 38291473, 2024). "The markers utilized in the conducted study, as defined by Tirosh and colleagues, successfully differentiated between various cell types, including melanoma cell (MLANA, PMEL), T cell (CD2, CD3D, CD3E, CD4, CD8A)." (PMID 37620327, 2023). "The CD8A gene expression mirrors CD8+ T-cell infiltration and a decrease in CD8+ T-cell numbers was observed in melanomas at progression on TT compared to at the baseline levels." (PMID 35892846, 2022). "Inducing lymph angiogenesis with a vaccine overexpressing VEGF-C (“VEGFC vax”) resulted in increased infiltration of CD8α+ cross-presenting DCs and CD8+ T cells and hence better tumor control in combination with anti-PD-1 in a B16 melanoma mouse model." (PMID 35626062, 2022). "CD8A exhibited good predictive performance, with 21 of 25 ICB-treated cohorts having an AUC greater than 0.5, among which two melanoma cohorts exhibited the strongest predictive likeliness for PD1 blockade." (PMID 36035168, 2022). "Analysis of the Cancer Genome Atlas melanoma dataset using a TRM core signature comprising of CD69, ITGAE, CD8A, TNFSRF18, 2B4 genes showed expression of TRM related genes was associated with survival in an ICI naïve population." (PMID 36466880, 2022). "The results indicated that CD8A and SELL were up-regulated as well as JAK2 was down-regulated in melanoma samples compared with normal controls (p-value < 0.05)." (PMID 32316408, 2020). "Higher proportions of NK cells, CD4+ and CD4+ CD8α+ T cells, and CD21− B cells among B cells are found in young melanoma-bearing piglets, consistent with the immune-mediated spontaneous regression in the MeLiM model." (PMID 32180771, 2020). "In conclusion, six hub genes (IRF1, JAK2, CD8A, IRF8, STAT5B, and SELL) were discovered to distinguish the response of melanoma patients under anti-PD-1 immunotherapy via WGCNA and integrated bioinformatics." (PMID 32316408, 2020). "The results of correlation analysis showed a significant, positive correlation (cor > 0.6, p-value < 0.05) between the expression of four hub genes (IRF1, CD8A, IRF8, and SELL) and three biomarkers in melanoma." (PMID 32316408, 2020). "We observed strong Pearson correlation coefficients between IL32 expression, found within the melanoma tumor and the surrounding microenvironment, and genes related to immune cell infiltration, such as CD3E (0.94), CD8A (0.89), IFNγ (0.75), and GZMB (0.86)." (PMID 30953519, 2019). "To assess the mRNA expression of four immunotherapy markers, CD274, PDCD1LG2, CD8A and IRF1, we used a multiplex RT-qPCR immunotherapy panel on the GeneXpert platform in melanoma patients treated with anti-PD-1 therapy." (PMID 31533832, 2019). "Notably, the combined expression of CCR9, CCL25, CD8A, and CD8B genes in tumors positively correlated with a higher DSS probability in patients with melanoma, with a better hazard ratio (HR) and P value compared to the expression of CD8A and CD8B genes only." (PMID 41042869, 2025). "In agreement, a positive correlation between CD8+ T‐cell reactivity markers such as CD8A (coding gene for CD8), PRF1 (as Perforin), GZMB (coding gene for Granzyme B) and ERRα was observed, as indicated by co‐expression analyses in different melanoma databases." (PMID 39888245, 2025). "CD8α:MyD88 T cells exhibited enhanced proliferation, cytokine production (IFN-γ, TNF-α), elevate cytotoxic activity, and increased costimulatory receptor expression, leading to tumor regression in a B16-F1 melanoma model." (PMID 40948803, 2025).
melanoma (continued). "Besides, we also employed immunohistochemical staining analysis in a cohort of 31 melanoma tissues, which revealed that the staining scores of XBP1 were highly correlated with those of CD8α and IFN-γ, respectively." (PMID 38291473, 2024). "Moreover, we grouped human melanoma samples from the TCGA database (SKCM) into immunological “hot” and “cold” tumor groups based on CD8A transcript levels serving as an indicator for tumor infiltrating lymphocytes." (PMID 39398277, 2024). "Furthermore, we compared tumor-infiltrating classic CD8a+ DCs population, synonymous with Batf3+ DCs, because this subset is a key orchestrator of immune responses in cancer and our previous work demonstrated that ptges depletion could enhance this population in melanoma." (PMID 37529399, 2023). "In the example of a melanoma BrM tissue section where tumor parenchyma was surrounded by inflammatory stroma (patient 16), densities of CD3E, CD4, CD8A, and CD8B transcripts were highest in the peritumoral inflammation and in the directly adjacent tumor parenchyma." (PMID 35584630, 2022). "When melanoma develops from the radial growth phase into nodular tumors, T cell activities reduce in the TME of these fish as demonstrated by decreased transcript levels of lck, cd4-1, and cd8α." (PMID 34095125, 2021). "Taken together, IRF1, JAK2, CD8A, IRF8, STAT5B, and SELL may serve as predictive therapeutic biomarkers for melanoma and could facilitate future anti-PD-1 therapy." (PMID 32316408, 2020). "Notably, even though γδ T cells and B cells were less frequent in melanoma-bearing pigs, there were higher proportions of CD21− MHC II+ B cells and CD8α+ γδ T in these animals." (PMID 32180771, 2020). "In line with this, laminarin-promoted CD8α+ cDCs and Ag specific CTL activation might induce specific killing of OVA-pulsed splenocytes and OVA-expressing B16 melanoma cells in vivo." (PMID 28423736, 2017). "In addition to the purity check upon cell sorting, potential CTL contamination in melanoma cell samples isolated from the co-cultures was checked by including a series of CTL markers on the NanoString (CD3D, CD3E, CD3G, CD8A and CD8B)." (PMID 27625650, 2016). "The expressions of CD8A, GZMA, GZMK and PRF1 genes in the NOS1-high-expression group were significantly lower than those in the NOS1-low-expression group, indicating that NOS1 might play an immunoregulatory role only in “cold” melanoma." (PMID 41535256, 2026). "Next, NK cells were sorted according to their expression of CD8α and CD70 and tested for their cytotoxicity against classical NK target cell lines 721.221 (B cell lymphoma) and K562 (myeloid leukaemia), as well as non-hematological tumor cell lines PC3 (prostate), A549 (lung) and Colo829 (melanoma)." (PMID 40046047, 2025). "Moreover, the mRNA expressions of two critical XBP1 target genes ERDJ4 and EDEM1 were also significantly correlated with PTPRC, CD8A and IFNG, respectively, indicating the potential facilitative role of IRE1α-dependent UPR branch in anti-tumor immunity in melanoma." (PMID 38291473, 2024). "As the aim of this work was to understand how melanoma TME affects the infiltration of CD8+ T cells, we excluded CD8+ T cell specific markers (CD8A, CD8B, GZMK and NKG7), as well as genes expressed in most CD8+ T cells (more than 50%) but in less than 10% of the remaining cells in the melanoma TME." (PMID 34040608, 2021). "Hence, combining with the results of survival and Cox regression analyses, it implied that the high expressions of IRF1, JAK2, CD8A, and SELL may predict a positive response to anti-PD-1 immunotherapy for melanoma patients." (PMID 32316408, 2020). "In addition, the T cell markers Cd3g and Cd8a showed a trend towards higher expression in NRF2 knockout tumors and quantification of CD3 + immune cell infiltration into control and NRF2 knockout melanomas showed a similar trend." (PMID 32978520, 2020).